GZMB (granzyme B)
Diseases named in the same sentence as GZMB in open-access papers (continued):
Sharing a sentence is not in itself a finding about the gene and the disease.
tumor (continued). "Granzyme B has been traditionally viewed as a primary mechanism used by NK cells to eliminate tumor cells." (PMID 33614475, 2020). "Activation of autophagy in RCC cells results in the degradation of NK-derived granzyme B (GZMB) which compromises the NK-mediated killing of tumor cells." (PMID 33643028, 2020). "Increased GzmB also supported endothelial cell migration and vessel formation, and promoted tumor angiogenesis, despite anti-VEGF treatments." (PMID 32318066, 2020). "A two-fold increase in Granzyme B accumulation was observed; Granzyme B production in the tumor microenvironment was increased (from 109.4 ± 54.7 pg/mL to 210.1 ± 67.3 pg/mL) in mice receiving lactobacilli." (PMID 32033490, 2020). "We defined tumors with simultaneous upregulation of PRF1 and GZMB (CytAct Up, z-Score = 0) as tumors with increased anti-tumor immunity." (PMID 32523042, 2020). "Immunofluorescence (IF) microscopy showed that NPM1 knockdown promoted CD8+ lymphocyte infiltration and granzyme B secretion in tumor tissues." (PMID 32245950, 2020). "This potentially reflects the differences in how GzmB was measured in the two tumor models as in the B16 F10 model, isolated cells were stimulated for 24 hours with anti-CD3 mAb prior to GzmB detection." (PMID 33428585, 2020). "Accordingly, elevated levels of Granzyme B in PyMT-IL-31 tumor model indicate enhanced cytotoxicity." (PMID 32843492, 2020). "When blocking the secretion of perforin from DNTs, the killing effect on tumor cells decreased by 80%-97%, which showed that DNTs exerted a killing effect that depended on the perforin/Granzyme B (GZMB) pathway." (PMID 32328176, 2020). "To examine the impact of cytokine- versus TCR-mediated stimulation on the expression of cytotoxic granules involved in tumor cell killing, we analyzed the expression level of granzyme B and perforin in differently stimulated γδ T cells by qPCR." (PMID 31947966, 2020). "Gene-gene interactions were detected in the relapse group; CCL5, GZMB, IL2RA, SELE, and CCL8 interacted with CCR5 in both the pCR and relapse groups and were associated with tumour progression, and metastasis." (PMID 33138797, 2020). "T-bet-deficient CD4+ T cells were able to control tumor growth even more effectively than WT CD4+ T cells in CD8 T-cell-depleted mice, supporting the relevance of CD4+GzmB+ T cells in tumor control induced by αCTLA-4." (PMID 31924474, 2020). "CD4+T and CD8+T cells assume tumor immunity through induction of perforin and Granzyme B secretion, activation of NK cells and direct killing." (PMID 32328188, 2020). "Cytotoxic molecules (i.e., granzyme B, perforin) was also increased in miR-340-5p-overexpressing tumor cells and significantly reversed by KMT5A-OE." (PMID 33168024, 2020). "It has been demonstrated that 5–30% of CD4+Foxp3+Tregs expressed a high level of granzyme B in tumor environments." (PMID 33519807, 2020). "In keeping with the production of GzmB, Trp1 cells expanded in lymphopenic hosts specifically killed B16 tumor cells in vitro." (PMID 31924474, 2020). "The altered T cell ratio resulted from a significant reduction in CD8+ T cells expressing granzyme B and IFNγ and from a significant expansion of CD39hiCD38hiPD-1hiCTLA4hiFoxp3hi Tregs at the tumour site." (PMID 32333046, 2020). "The tumor morphology was altered with atrophy of tumor cells in discrete islands with strong staining for granzyme B and surrounded by fibrous connective tissues, a phenomenon commonly observed post tumor regression." (PMID 33426543, 2020). "NK cells at the tumor site expressed low levels of granzyme B and CD57, as well as low levels of IFNγ." (PMID 33276569, 2020). "The most important and promising predictive biomarkers under evaluation are PD-L1 expression, tumor mutational burden (TMB), immune cell gene expression profiling, CD8+ cells and Granzyme B, molecular subtyping." (PMID 33194654, 2020).
tumor (continued). "GSDME cleavage at D270 by GzmB/caspase 3 promoted pore formation to induce pyroptosis and suppress tumour growth through the enhancement of anti-tumour adaptive immunity." (PMID 32404864, 2020). "It was shown that release of granzyme B induces apoptosis and leads to tumor suppression in the MDA-MB-231 breast cancer mouse model." (PMID 33298099, 2020). "GZMB was up-regulated in CA tumors and down-regulated in AA tumors when compared to their matching non-tumor controls." (PMID 32983990, 2020). "They encounter injected γδT cells either in peripheral blood or in the tumor microenvironment and stimulate them to produce more cytotoxic cytokines, such as granzyme B and perforin, to destroy tumor cells." (PMID 32849498, 2020). "CD4+ transfer into lymphodepleted animals or regulatory T (Treg) cell depletion promoted GzmB expression by tumor-infiltrating CD4+, and this was prevented by interleukin-2 (IL-2) neutralization." (PMID 31924474, 2020). "Although glucose starvation significantly reduced the tumour-killing capacity and the expression of granzyme B, TNF-α and IFN-γ of Teff cells, both glucose and inosine supplementation restored these properties in mouse and human Teff cells." (PMID 32694789, 2020). "In these three groups, we compared immune infiltrates, such as TIL phenotypes and extent, and the intra-tumor expression of the cytotoxic molecule granzyme B (GZB)." (PMID 32075608, 2020). "Tumor-infiltrating CD8s are largely activated, expressing cytotoxic effectors such as Perforin and Granzyme B (including plentiful IFNγ), which are scarce in murine CD8s located in lymphoid organs at homeostasis." (PMID 32322254, 2020). "Another mechanism is the sensitization to cytotoxic T lymphocytes by upregulating mannose-6-phosphate receptors on tumor cells, which increases the permeability of the membrane to granzyme B, leading to cancer cell death independent from perforin." (PMID 33643895, 2020). "After CD8+ T cells recognize tumor cells, they release their cytolytic granules containing perforin and granzyme B to induce apoptosis in tumor cells." (PMID 30934955, 2019). "We observed an increase in CD8+ T cell tumor infiltration and a higher level of cytoplasmic Granzyme B after CTX/L-NIL and combinatory treatment." (PMID 30646957, 2019). "In particular, T cells in the tumor proximity (peritoneum) presented higher perforin, granzyme B, lower IL-10 and a more beneficial mRNA profile, compared to classical GM4-1 step vaccination." (PMID 30621204, 2019). "T cells from p-Tvax vaccinated mice were also demonstrated to recognize and attack tumor cells by secreting Granzyme B in ELISPOT assays performed with different MM cell lines." (PMID 31428586, 2019). "The cytotoxic granzyme B (GrB)/perforin pathway has been traditionally viewed as a primary mechanism that is used by cytotoxic lymphocytes to eliminate tumor cells." (PMID 31372243, 2019). "Expression of PD-L1 on tumor cells or macrophages can reduced Granzyme B and IFN-γ expressed by CD8+ T cells, leading to the dysfunction of cytolytic activity in CD8+ T cells." (PMID 31572677, 2019). "The present study indeed also reports that CD8+ T cells infiltrating the tumor harbor an activated/cytotoxic phenotype eliciting PD-1/Granzyme B expression." (PMID 31244851, 2019). "After 48 hours of CD20xCD3 bsAb treatment, T cells cultured with a mixture of JeKo-1 and RL tumor cells strongly up-regulated IFNγ and Granzyme B, indicating that the T cells were effectively activated." (PMID 31882897, 2019). "Upon transfer into melanoma-bearing hosts, these cells accumulate in the tumor site, become activated by tumor antigens, and express the cytolytic factor granzyme B, resulting in tumor regression." (PMID 31569642, 2019). "For Bregs, granzyme B expressing Bregs, induced by tumor cells and IL-21, react to tumor cells and promote tumor immune escape." (PMID 31662750, 2019).
tumor (continued). "Taken together, we have determined that IFN-I regulates CTL effector function through activating the STAT3-granzyme B axis in anti-tumor immune response." (PMID 31228946, 2019). "Activated CD8+ T cells have direct cytotoxic activity against tumour cells via the expression of cytotoxic perforin/granzyme-B and IFN-γ46." (PMID 31519961, 2019). "The main factors in T cells anti-tumor cytotoxicity include IFNγ, granzyme B, and perforin secretion." (PMID 31514488, 2019). "NKG2D, granzyme B and perforin upregulation was tumor independent because the same pattern was observed in all treatments without tumor inoculation." (PMID 31307539, 2019). "Cx43-GJIC does not affect tumor-induced NK-cell degranulation but regulates an efficient Ca2+ influx into the target tumor cells, which contributes to granzyme B (GrzmB) activity inside target tumor cells, leading to cell apoptosis." (PMID 31547237, 2019). "At higher co-culture ratios of B to T cells, the T cells cultured with B cells derived from tumor draining lymph nodes of cobimetinib treated mice also exhibited more interferon-gamma and granzyme B expression than those which received vehicle alone." (PMID 31671149, 2019). "Tumor-infiltrated CD8 lymphocytes are the primary sources of antitumor immunity, with their activation characterized by presentation of CD107a and the production of granzyme B and perforin, which kill tumor cells." (PMID 31409352, 2019). "Peripheral and tumor-associated NK cells in STAT3-targeted tumor-bearing mice, exhibit higher expression of the NK activation markers NKG2D, CD69, Fas ligand (FasL), granzyme B, perforin, and IFNγ, resulting in reduced tumor growth and enhanced survival." (PMID 31057536, 2019). "Our data determined that IFN-I is not essential for CTL activation but rather is critical in regulation of key CTL effector granzyme B expression and tumor growth control in vivo." (PMID 31228946, 2019). "Natural killer (NK) cells-derived exosomes have also been shown to mediate anti-tumor activities via its cellular content perforin and granzyme B, which has cytotoxic activity against various tumor cell lines." (PMID 31555295, 2019). "Consistent with the immunostaining results, flow cytometry analysis of tumor-infiltrating lymphocytes (TILs) showed that anti-DKK2 antibody treatment increase the percentage of GZMB+ T cells." (PMID 31372243, 2019). "Cross linkage of T cells to the tumor cells causes T cells to release cytotoxic molecules such as perforin, which creates transmembrane pores in tumor cells, and granzyme B, which initiates apoptosis toward tumor cells." (PMID 31781214, 2019). "Tumour infiltrating T cells isolated 3 weeks after TC-1 tumour transplantation, secreted less IFNγ, perforin and Granzyme B compared with those isolated 2 weeks after TC-1 tumour inoculation." (PMID 31277636, 2019). "Both CD4+ and CD8+ T cells cultured with Raji or JeKo-1 tumor cells exhibited increased expression of the effector molecules Granzyme B and IFNγ." (PMID 31882897, 2019). "Peripheral and tumor-associated NK cells from STAT3-targeted tumor-bearing mice expressed elevated levels of NK activation markers NKG2D, CD69, Fas ligand (FasL) granzyme B, perforin, and IFNγ, resulting in reduced tumor growth and enhanced survival." (PMID 31057536, 2019). "As expected, N-803 + αPD-L1 treatment significantly increased the population of NK cells expressing the cytolytic molecule Granzyme B in the primary tumor, lung vasculature, and spleen versus PBS and αPD-L1 treatments." (PMID 30898149, 2019). "Cytotoxic markers for ENKL diagnosis include TIA-1, granzyme B, T-cell intracellular antigen 1 and perforin on tumor cells." (PMID 31139570, 2019).
tumor (continued). "Ultimately, the transduced CAR helps these engineered T cells to mediate a redirected response toward antigen positive tumor cells, which involves both granzyme-B and perforin for tumor lysis as well as generation of inflammatory cytokines and chemokines." (PMID 32076597, 2019). "Analysis of the whole-tumor lysates from Camkk2−/− mice showed a remarkable upregulation of genes expressed in the cytotoxic effector lymphocyte subsets, such as Granzyme B (Gzmb) and Perforin-1 (Prf1) (top)." (PMID 31164648, 2019). "CD8+ Tcells effect tumor killing in two ways; (i) through the secretion of cytotoxic molecules (granzyme B and perforin) and, (ii) through the secretion of proinflammatory cytokines (IL-2, TNF-α, and IFN-g)." (PMID 30979375, 2019). "The percentage of Granzyme B+Perforin+CD8+ tumor-infiltrating lymphocytes (TILs) negatively correlates with the percentage of B7-H4+ cells in tumors." (PMID 30813210, 2019). "iNKT cells can be activated by direct interaction with tumor cells: CD1d+ tumor cells present endogenous glycolipids via CD1d which is then recognized by the T-cell receptor of iNKT cells leading to perforin/granzyme B or Fas/FasL-mediated cytotoxicity." (PMID 31354710, 2019). "The expression of IFN-γ (a), anti-tumor molecules perforin (b) and granzyme B (c) in tumors of mice on day 21 after tumor cell injection were compared (n = 5)." (PMID 30808413, 2019). "Together, these data suggest that CD8+NKT-like cells exert cytotoxicity against tumor cells and MDSCs through a granzyme B-mediated granule exocytosis pathway." (PMID 31278476, 2019). "Taken together, our results suggest that GzmB expression in MDSCs is another means to promote tumor growth and warrants further investigation to unravel the exact underlying mechanism." (PMID 31212684, 2019). "To further understand the activation extent of tumor-infiltrating CD8+ T cells we examined paired pre and post DC vaccine tumor samples for the presence of Granzyme B (GZMB), a key functional marker of effector cytotoxic CD8+ lymphocytes." (PMID 31649669, 2019). "We indeed found that PD-L1-specific HTLs showed cytotoxicity against tumor cells in vitro with producing granzyme B and inhibited tumor growth in vivo." (PMID 31221178, 2019). "Knockdown of this receptor enhanced the synthesis and release of PGE2 by the tumor cells and reduced the release of granzyme B by cocultured Vδ1 T cells thereby inhibiting Vδ1 T cell-cytotoxicity." (PMID 31555275, 2019). "After complex recognition of target cells by T and B cells, delivery of the serine protease granzyme B (GrB) to tumor cells comprises the cytotoxic insult resulting in a well-characterized, multimodal apoptotic cascade." (PMID 31362764, 2019). "Staining of granzyme B reflected the significant presence of CTLs and NK cells in the tumor nodules, in response to Rb9, and represents the signature of immune effector cells infiltrating the lung tissue." (PMID 32010152, 2019). "To assess why some PDA cell lines are resistant to CAR T cell killing independent of their tMUC1 expression or the CAR T cell’s ability to express perforin, or produce IFN-γ and granzyme B, we considered some common immune evasion tactics used by tumor cells." (PMID 31514488, 2019). "CD8+ T cells also expressed more Granzyme B in the primary tumor with N-803 + αPD-L1 treatment versus PBS and N-803 treatments." (PMID 30898149, 2019). "These cells can kill tumor cells by direct cytolysis using perforin and granzyme B, but also by modulating the recruitment of other effector immune including T cells, B cells, NK cells and DCs." (PMID 30974896, 2019). "GzmB (granzyme B) is present in NK cells and activated cytotoxic T cells and plays an important role in inducing tumor cells to undergo apoptosis." (PMID 30774761, 2019). "The percentage of CD8, IFN-γ, Granzyme B and Perforin were 12.0, 6.4, 19.8 and 6.9% in tumor tissues respectively, compared to 19.9, 16.7, 44.1 and 16% in adjacent normal tissues (n = 17)." (PMID 30744691, 2019).
tumor (continued). "Flow cytometric analysis revealed that lenvatinib reduced tumor-associated macrophages (TAMs) and increased the percentage of activated CD8+ T cells secreting interferon (IFN)-γ+ and granzyme B (GzmB)." (PMID 30811474, 2019). "Our data so far indicated that the administration of poly A:U alone at the tumor site, was capable of increasing the frequency of granzyme B+ CD8+ T cells." (PMID 30949170, 2019). "To further investigate the activation status of the CD8+ T cells that infiltrated the tumor, we assessed the cytotoxic T cell phenotype by using a specific marker, Granzyme B, and for activated T cell phenotype, PD-1." (PMID 31244851, 2019). "Neo-epitope-specific CD8+ T cells displayed high expression of other effector molecules, such as TNF-α, granzyme B and IL-2, which is consistent with anti-tumor cytotoxic activity." (PMID 31562311, 2019). "Secondly, we analyzed the amount of key effector molecules – IFN-γ, TNF-α, perforin and granzyme B – that are induced by NK101 or NK-92 after tumor cell co-culture." (PMID 31126350, 2019). "This enhanced anti-tumor effect is accompanied by a marked increase in CD8 + tumor-infiltrating T-cells (TILs) expressing killer effector molecules granzyme B (GZMB) and interferon γ-1 (IFNγ1)." (PMID 31641113, 2019). "Together with the description of perforin and GzmA and GzmB expression in immature DCs, this suggests that GzmB and perforin expression in myeloid cells is not only related to tumor development, but can be considered a general feature of myeloid cells." (PMID 31212684, 2019). "Two NKT subsets have been identified: type I induce the lysis of tumor cells directly via a perforin/granzyme B-mediated mechanism or indirectly via the activation of NK cells and DCs; type II show immunosuppressive activity through the production of IL-13." (PMID 31412566, 2019). "One of the major mechanisms of NK mediated tumor cell killing is degranulation, i.e., the release of Granzyme B and Perforin by the effector cell." (PMID 30634595, 2019). "The release of cytotoxic granules containing perforin (PRF1) and GZMB by NK cells is one of the major mechanisms responsible for tumor cell killing by NK cells." (PMID 31540045, 2019). "Our conclusions are supported by results showing that the inhibition of GZMB activity in tumor cells affected the anti-tumor activity of LipA." (PMID 29983866, 2018). "Using a newly characterized and culturable murine NK cell line, we demonstrated that WEE1 kinase inhibition can be used to prevent G2/M cell cycle checkpoint activation and sensitize tumor cells to granzyme B-dependent NK lysis." (PMID 29925431, 2018). "Taken together, these data suggest that GZMB from neutrophils contributed to tumor cell apoptosis in LipA treated rats." (PMID 29983866, 2018). "We demonstrated that all our immune biomarkers, except for PD-L1, had a strong correlation across tumor-nest and TME compartments, with CD8 and Granzyme B being the TIL markers with strongest association." (PMID 29874226, 2018). "We found that the frequency of granzyme B-expressing CD8+ T cells was significantly lower in SN (p<0.001) when compared to either PBMC or tumor." (PMID 29966014, 2018). "Mechanistically, treating the rats with the Lipid A analog triggered granzyme B release from neutrophils in tumor cell vicinity, which was correlated to tumor regression." (PMID 29983866, 2018). "Consistently, analysis by flow cytometry and immunohistochemical staining showed that tumor-infiltrating OT-I T cells upregulated IFN-γ and granzyme B within the tumor tissues." (PMID 29491374, 2018). "Consistent with their enrichment with the liver-resident subset, both intrahepatic and tumor NK cells tended to have reduced granzyme B compared to circulating NK cells." (PMID 29867983, 2018). "The inhibition of miR-23a enhances granzyme B expression in human CTLs and robustly hinders tumor progression in mice with established melanoma tumors." (PMID 30443251, 2018).